MEOX2 (mesenchyme homeobox 2)
Diseases named in the same sentence as MEOX2 in open-access papers (continued):
Sharing a sentence is not in itself a finding about the gene and the disease.
atherosclerosis (3 papers, 2011 to 2023). A disease characterized by the build-up of fatty material and calcium deposition in the arterial wall resulting in partial or complete occlusion of the arterial lumen. "Microarrayanalysis has shown that MEOX2 expression is increased 10-fold in cells fromHutchison-Gilford Progeria Syndrome patients.Thus, MEOX proteins may play a role in endothelial aging and atherosclerosis,by inhibiting cell cycle progression and inducing endothelial cell senescence." (PMID 22206000, 2011).
heart failure (3 papers, 2015 to 2024). Inability of the heart to pump blood at an adequate rate to meet tissue metabolic requirements. "In our population study, we therefore also searched for association between the incidence of well-documented heart failure and variation in the MEOX2 and TCF15 genes." (PMID 26428460, 2015). "Examples of angiogenesis-related genes that are specifically induced in human heart failure but not in mouse models include receptors such as the VEGF-receptor FLT1 or transcription factors like the mesenchyme homeobox protein 2 (MEOX2)." (PMID 38573186, 2024). "Since a reduced FA oxidation capacity causes energy starvation in a failing heart, modulating the technology of TEFA transport via several possible pathways, including PPARγ, Notch, and Meox2/TCF15, might open a new avenue to developing therapeutic strategies for energy-starved heart failure." (PMID 34940647, 2021). "Our experimental studies demonstrated that the MEOX2/TCF15 heterodimer facilitates the transport of fatty acids across cardiac endothelial cells and that in mice haplodeficiency in these genes results in impaired contractility of cardiomyocytes and heart failure." (PMID 26428460, 2015).
melanoma (3 papers, 2017 to 2024). A malignant, usually aggressive tumor composed of atypical, neoplastic melanocytes. "Differentially methylated genes included three non-melanoma related genes (MEOX2, OLIG3, PON3), but previously associated with DNA methylation and cancer prognosis in other pathologies." (PMID 28578692, 2017). "Here, we identified, and validated in an independent validation cohort, three genes (MEOX2, OLIG3, and PON3) for which the degree of DNA methylation can predict the prognosis of melanoma patients." (PMID 28578692, 2017).
breast tumor (2 papers, 2019 to 2020). "Our results support previous literature, as we observed a reduction in MEOX2 expression in breast tumors." (PMID 33087122, 2020). "Recent research shows that MEOX2 can up-regulate p21 which is very important for breast tumor grading." (PMID 31874629, 2019).
cervical cancer (2 papers, 2014 to 2024). A primary or metastatic malignant neoplasm involving the cervix. "Supporting the idea that MEOX2 and TWIST1 contribute to oncologic treatment resistance, functional studies have shown that shRNA-mediated TWIST1 silencing in cisplatinum-treated cervical cancer cells regulates the expression of the multi-drug resistance receptor, MDR1/P-gp, also known as ABCB1." (PMID 25460568, 2014).
cleft palate (2 papers, 2020 to 2024). Cleft palate is a fissure type embryopathy that affects the soft and hard palate to varying degrees. "Importantly, 6 of these 39 MEOX2 targets have previously been associated with cleft palate, which represents a significantly larger overlap than expected by chance (Fisher’s Exact test, P value = 0.0002, odds ratio = 9.2)." (PMID 38280850, 2024). "Msx1, Meox2, and Pax9 genes display distinct expression patterns during mammalian palatogenesis and mutations in these genes cause developmental defects, typically a cleft palate." (PMID 32850780, 2020).
colorectal cancer (2 papers, 2014 to 2021). A primary or metastatic malignant neoplasm that affects the colon or rectum. "In addition, MEOX2 promoter sequences were recently used as part of a test for cancer-specific DNA methylation cluster markers in colorectal cancer, and TWIST1 methylation was assessed at promoter sequences in lung AD patients." (PMID 25460568, 2014).
coronary artery disease (2 papers, 2015 to 2017). "Interestingly, Meox2 has been implicated in directing expression of heart EC-specific genes and in the pathogenesis of coronary artery disease." (PMID 28121289, 2017).
Wilms tumor (2 papers, 2010 to 2024). An embryonal neoplasm characterized by the presence of epithelial, mesenchymal, and blastema components. "Meox2 is a developmental homeobox protein and potential tumor suppressor identified in Wilms tumor, arising from the developing kidney." (PMID 39310276, 2024). "In Wilms tumors, a consensus region of LOH has been identified within 7p21 containing ten known genes, including two candidate tumor suppressor genes, mesenchyme homeobox 2 (MEOX2) and sclerostin domain containing 1 (SOSTDC1)." (PMID 21080955, 2010).
astrocytoma (1 paper, 2023). "MEOX2 was detected only in one astrocytoma (grade 2, 1% of cells, mHS 2) and one oligodendroglioma (grade 3, 8.5% of cells, mHS 12.75)." (PMID 37568909, 2023).
brain tumors (1 paper, 2021). "This work paves the way toward a better understanding of the role of MEOX2 in the pathophysiology of primary brain tumors." (PMID 34885053, 2021).
cystic kidneys (1 paper, 2010). "Pkd1cond/−, Meox2-Cre+ mice also exhibited cystic kidneys, edema, and polyhydramnios but a substantial fraction survived to birth (∼16/102, expected ∼25/102)." (PMID 20862291, 2010).
Gliosis (1 paper, 2023). Gliosis is the focal proliferation of glial cells in the central nervous system. "The sensitivity and specificity of the negative staining for the diagnosis of gliosis were as follows: EGFR—100% sensitive, 32.8% specific; MEOX2—97.7% sensitive, 37.5% specific; SOX11—79.5% sensitive, 46.6% specific and INSM1—97.7% sensitive, 47.8% specific." (PMID 37568909, 2023).
lung adenocarcinoma (1 paper, 2017). A carcinoma that arises from the lung and is characterized by the presence of malignant glandular epithelial cells. "However, survival analysis of only lung adenocarcinoma patients with EGFR-non-mutated status identified poorer overall survival (statistically significant at p≤0.005) with higher MEOX2 and GLI-1 protein co-expression levels (p=0.045 and p=0.006, respectively)." (PMID 28978016, 2017). "Furthermore, an inducible, cisplatinum dose-dependent MEOX2 protein expression pattern was identified in lung adenocarcinoma cells, corresponding to cisplatinum-induced GLI-1 protein expression in the lung adenocarcinoma cell lines A427 and A549 that was markedly reduced by anti-MEOX2 siRNAs." (PMID 28978016, 2017). "To confirm this hypothesis, we quantitatively validated the MEOX2 occupancy of GLI-1 gene promoter sequences in 13 lung samples from patients with adenocarcinoma and in the lung adenocarcinoma cell lines A427 and A549." (PMID 28978016, 2017). "Cellular migration and proliferation were systematically analyzed in functional assays, and significant (p≤0.001) MEOX2-dependent GLI-1 protein expression was present in A549 cells, which contrasted with non-detectable MEOX2 levels in the H1975 lung adenocarcinoma cell line." (PMID 28978016, 2017).
malignant glioma (1 paper, 2022). A grade III or grade IV glioma arising from the central nervous system.
mantle cell lymphoma (1 paper, 2023). Mantle cell lymphoma is a rare form of malignant non-Hodgkin lymphoma affecting B lymphocytes in the lymph nodes in a region called the ``mantle zone''. "However, for setting up SOX11, INSM1, and MEOX2 assays, tissues with the strongest expression were chosen, given the lack of weak expressing tissues and general need to identify strong expressing cells of mantle cell lymphoma (SOX11), neuroendocrine tumours (INSM1), and endothelium (MEOX2)." (PMID 37568909, 2023).
non-small cell lung carcinoma (1 paper, 2025). A group of at least three distinct histological types of lung cancer, including non-small cell squamous cell carcinoma, adenocarcinoma, and large cell carcinoma. "Moreover, experimental studies indicate that the MEOX2 and GLI-1 transcription factors can influence the genetic expression of EGFR, a key driver gene of non-small cell lung carcinomas (NSCLC), by modulating specific histone marks on its enhancer and promoter sequences." (PMID 39971779, 2025).
periodontitis (1 paper, 2020). An acute or chronic inflammatory process that affects the tissues that surround and support the teeth. "After these confirmations, we conducted the in vivo experiment of periodontitis-induced animal model for the examination of Meox2 down-regulation in tooth loss lesion." (PMID 33218046, 2020). "We also examined the possibilities of increased Meox2 localization in tooth loss lesion due to the severe periodontitis." (PMID 33218046, 2020). "In the present study, we down-regulated the expression level of Meox2, in which its developmental function in palatogenesis is revealed and applied into tooth loss lesion due to severe periodontitis for the accommodation of the keratinization of oral mucosa and promotion of the bone formation." (PMID 33218046, 2020). "In this study, we have demonstrated the detailed function of Meox2 and its related signaling pathways involved in bone healing processes using siRNA treatment against Meox2 in the extraction socket by local delivery method as a gene therapy after tooth loss following periodontitis induction." (PMID 33218046, 2020).
skin cancer (1 paper, 2019). "Again, no indications of any MEOX2-specific aberrant splicing incidents could be recognized for all three types of skin cancer herein analyzed." (PMID 30795533, 2019).
squamous cell carcinoma (1 paper, 2017). A carcinoma arising from squamous epithelial cells. "Subsequently, down-regulated genes (FAS, PTPRB, MEOX2 and RECK) were considered where lower expression of the genes correlated with poor prognosis in lung adeno- but not so in squamous cell carcinoma patients." (PMID 29254206, 2017).
tumor (21 papers, 2010 to 2025). "We identified Cathepsin S (CTSS), which is from the Cathepsin family of cysteine proteases, has been implicated in an important role for tumor development and progression, as a MEOX2 downstream target." (PMID 35436995, 2022). "In our previous work, we showed that MEOX2 was associated with a poor patient prognosis but its biological involvement in tumor development remains ill defined." (PMID 34885053, 2021). "Similarly to MEOX2, at tumor scale, HOXA13 upregulation was associated with enhancement of focal adhesion mediated by integrins and reduction of MAPK pathway activation." (PMID 34885053, 2021). "In vivo tumor xenograft assays using nu-/nu- mice showed that shMEOX2 significantly decreased tumor size, indicating MEOX2 promotes lung tumor growth." (PMID 39971779, 2025). "Similar to the EGFR gene, MEOX2 is localised on chromosome 7, and gains of chromosome 7 can, in part, explain its expression in a subset of tumours." (PMID 37568909, 2023). "Subsequently, expression of MEOX2 in GSC seems to be consistent with strong expression in the tumor." (PMID 34885053, 2021). "We had previously demonstrated that the expression of MEOX2 in the tumor tissue correlates with its methylation profile and with wild-type IDH1/2." (PMID 34885053, 2021). "In our study, MEOX2 expression in GSC was consistent with its expression in the original tumor." (PMID 34885053, 2021). "Representative protein expression of MEOX2, PHYHIP, RBBP8, ST18, TCF12, and THRB in tumor tissues was demonstrated based on immunohistochemical analysis in the HPA database." (PMID 40869909, 2025). "Therefore, MEOX2 might repress tumor development by inhibiting angiogenesis." (PMID 35615155, 2022). "Back at the tumor tissue from which GSC2, 6 and 10 were derived, IHC analysis confirmed the strong nuclear expression of MEOX2." (PMID 34885053, 2021). "When expressed, MEOX2 was well localized in the nucleus in GSC and in tumor tissue." (PMID 34885053, 2021). "Finally, another study reported higher expression of MEOX2 in GBM and tumor-derived GSC, compared with conventional cell lines." (PMID 34885053, 2021). "Methylation of MEOX2 promoter correlated with IDH1 mutation status and was independent of tumor grade (WHO, 2016 classification) (p < 0.001)." (PMID 34885053, 2021). "These genes likely function as downstream effectors of STAT3 in GBM to regulate not only cell proliferation (e.g., GAS7, IGFBP2, MEOX2 and MXI1), and but also tumor-stroma interactions by modulating protein secretion (e.g., ANXA1, ARL4C, EMILIN1, EMP2, EXTL3 and PDIA4)." (PMID 29774125, 2018). "MEOX2 and PHYHIP, showed no significant protein expression in tumor tissues; the THRB showed “low intensity”, RBBP8 and ST18 showed “medium intensity”, and, interestingly, the TCF12 showed “high intensity”." (PMID 40869909, 2025). "In our cohort, MEOX2 immunoreactivity was significantly higher in the subset of EGFR-amplified GBMs (96.7%, 29/30); it was commonly seen in the rest of the GBMs (70.2%, 33/47) and only rarely observed in IDH1mt tumours (5.9%, 2/34) and non-diffuse gliomas (4.3%, 1/23)." (PMID 37568909, 2023).
cancer (14 papers, 2014 to 2025). A tumor composed of atypical neoplastic, often pleomorphic cells that invade other tissues. "This protein is considered as an oncogene frequently associated with poor outcomes; a gatekeeper is linked to other proteins as MEOX2 whose possible function in some cancers is to be a suppressor gene." (PMID 33649335, 2021). "Given that self-renewal is a key aspect of cancer stem cells, we tested if MEOX2 depletion affected BT273 and BT379’s ability to reassemble into new spheres after dissociation to single cells." (PMID 35565433, 2022). "MEOX2 is a transcription factor that plays a wide range of roles in cell development and in cancer, functioning as either a direct or indirect activator of its target genes." (PMID 35565433, 2022). "MEOX2 is a transcription factor that has also been studied in cancer due to its growth arresting properties." (PMID 33087122, 2020). "When examining the top 100 gene pairs, BSDC1, C3orf14, CDR2L, LRRC42, MEOX2, NRG2, and PLEKHA6, and SCARF1 were consistently identified by feature selection methods to be associated with cancer status." (PMID 33087122, 2020). "C3orf14, CDR2L, LRRC42, MEOX2, NRG2, and SCARF1 have been previously associated with cancer." (PMID 33087122, 2020). "Besides, MEOX2 is reported as an oncogene or tumor suppressor gene in various cancers." (PMID 35436995, 2022). "Furthermore, inhibition of MEOX2 severely impaired F-actin polymerization, which is an essential process for actin assembly and cytoskeleton construction, and also is fundamental for cancer cell motility." (PMID 35436995, 2022). "MEOX2 and RNA Pol II occupancy on the GLI-1 gene promoter was differentially enriched, likely correlating with different clinical parameters such as overall survival time and/or cancer drug response." (PMID 28978016, 2017). "In addition, MEOX2 contributed to cell viability and proliferation through the AKT/extracellular‐signal‐regulated kinase pathway and was involved in regulating the phenotype and adhesion properties of cancer stem cells." (PMID 38090653, 2022). "Interestingly, C3orf14, CDR2L, LRRC42, MEOX2, NRG2, and SCARF1 are known carcinogenic genes, while BSDC1 and PLEKHA6 have not been described in previous cancer literature." (PMID 33087122, 2020). "However, MEOX2, which is a nonclassical HOX gene, has seldom been reported in human cancers." (PMID 35436995, 2022).
digestive system cancer (1 paper, 2022). A primary or metastatic malignant neoplasm involving any part of the digestive system. "The study has shown that MEOX2 is a novel biomarker associated with macrophage infiltration in digestive system cancer." (PMID 36685873, 2022).
MEOX2 also shares sentences with these, for which no sentence is quoted: hepatocellular carcinoma (3 papers); gastric cancer (2); ovarian carcinoma (2); pulmonary hypertension (2); adenocarcinoma (1); cardiovascular disorder (1); Congenital Insensitivity to Pain (1); COVID-19 (1); cutaneous melanoma (1); endothelial dysfunction (1); ependymoma (1); epilepsy (1); ganglioglioma (1); glioneuronal tumours (1); Hutchinson-Gilford progeria syndrome (1); hypokalemic periodic paralysis, type 1 (1); infertile (1); lung disease (1); Mowat-Wilson syndrome (1); neuroendocrine tumours (1); neurological disorder (1); Obesity (1); oligodendroglioma (1); oral cancer (1); osteosarcoma (1); periodic paralysis (1); pilocytic astrocytoma (1); prostate carcinoma (1); rectal cancer (1); respiratory disorders (1).
A further 2 diseases each share a sentence with MEOX2 in 1 paper.